SMARCB1 (SWI/SNF related BAF chromatin remodeling complex subunit B1)
Diseases named in the same sentence as SMARCB1 in open-access papers (continued):
Sharing a sentence is not in itself a finding about the gene and the disease.
spinal chordoma (1 paper, 2024). A slow-growing malignant bone tumor arising from the remnants of the notochord and occurring in the spine. "In conclusion, partial SMARCB1/INI1 loss, mostly due to 22q deletion, was detected in a significant number of patients with conventional spinal chordomas and was correlated with mobile spine location and inadequate surgical margins." (PMID 39199581, 2024). "We retrospectively analyzed 89 patients with conventional spinal chordomas to investigate the differences in the immunohistochemical expression of SMARCB1/INI1 and the underlying genetic alterations in the SMARCB1 gene." (PMID 39199581, 2024). "Partial SMARCB1/INI1 loss was identified in 37 (41.6%) patients with conventional spinal chordomas (27 mosaic and 10 clonal)." (PMID 39199581, 2024). "The FISH analysis performed on 37 conventional spinal chordoma patients with focal SMARCB1/INI1 loss revealed three possible molecular patterns." (PMID 39199581, 2024). "However, the genomic studies in the literature revealed that the loss of chromosome 22 or the monoallelic deletion of SMARCB1 is rare in conventional spinal chordomas." (PMID 39199581, 2024). "In our study, the immunohistochemical pattern of SMARCB1/INI1 in conventional spinal chordomas was analyzed for the first time, and partial loss of SMARCB1/INI1 was observed in 41.6% of cases." (PMID 39199581, 2024). "In conclusion, we retrospectively analyzed 89 cases of conventional spinal chordoma, and two distinct expression patterns (mosaic and clonal) of partial SMARCB1/INI1 loss were observed." (PMID 39199581, 2024).
Telangiectasia (1 paper, 2020). Telangiectasias refer to small dilated blood vessels located near the surface of the skin or mucous membranes, measuring between 0.5 and 1 millimeter in diameter. "Next-generation sequencing revealed mutations in the ataxia telangiectasia-mutated (ATM), SWI/SNF-related matrix-associated actin-dependent regulator of chromatin subfamily b-member 1 (SMARCB1), and phosphoinositide-3-kinase regulatory subunit 1 (PIK3R1) genes." (PMID 32537438, 2020).
testicular cancer (1 paper, 2025). A primary or metastatic malignant neoplasm that affects the testis. "There is currently a lack of reports on SMARCB1/INI1-deficient testicular cancer." (PMID 40115023, 2025).
testicular seminoma (1 paper, 2025). A malignant germ cell tumor arising from the testis. "In the differential diagnosis between SMARCB1/INI-1-deficient tumors and testicular seminoma in this case,The negative expression of OCT4 is a breakthrough point in the diagnosis of testicular seminoma in this case." (PMID 40115023, 2025). "Although the postoperative immunohistochemistry showed the loss of SMARCB1/INI-1 expression and the negative expression of OCT4, considering the location of the tumor and the patient’s age, the patient still received adjuvant chemotherapy for testicular seminoma after surgery." (PMID 40115023, 2025).
testicular tumor (1 paper, 2025). "The patient with a SMARCB1-deficient testicular tumor reported in the present study experienced disease progression and multiple metastases only 4 months after the surgery, which shows that tumors with SMARCB1 deficiency are highly malignant and invasive." (PMID 40115023, 2025). "In April 2023, the puncture biopsy sample admitted to the Cancer Hospital Affiliated to FuDan University (China, Shanghai) for pathological consultation and was diagnosed with differentially differentiated cancer (testicular tumor) consistent with SMARCB1/INI-1 deletion." (PMID 40115023, 2025).
thyroid cancer (1 paper, 2020). "We found 16 SMARCB1 mutation descriptions out of 1328 tested thyroid cancer samples in COSMIC." (PMID 32380731, 2020). "To preliminarily assess whether SMARCB1 was differentially expressed in thyroid cancer, we examined a microarray dataset downloaded from GEO (series number GSE6004)." (PMID 32380731, 2020). "We speculate that SMARCB1 is an important effector in addition to NF2 and CHEK2 inactivation among thyroid cancers with chromosome 22q loss." (PMID 32380731, 2020).
triple-negative breast carcinoma (1 paper, 2019). An invasive breast carcinoma which is negative for expression of estrogen receptor (ER), progesterone receptor (PR), and human epidermal growth factor receptor 2 (HER2). "Mutated in 20% of human cancers; doxorubicin resistant triple-negative breast cancer is associated with loss of SMARCB1, SMARCA4, or KEAP1 (a BRCA1 interactor)." (PMID 31287417, 2019).
urothelial carcinoma of the renal pelvis (1 paper, 2025). "Similarly, urothelial carcinoma of the renal pelvis shows expression of INI1/SMARCB1, maybe positive for PAX-8, and tends to occur in older patients." (PMID 40777608, 2025).
tumor (540 papers, 2001 to 2026). "In the context of SMARCB1 mutations or SS18 fusion proteins, ncBAF complex activity is increased and compensates for the loss of cBAF and PBAF function; hence, SMARCB1 mutant tumor cells are explicitly vulnerable to perturbation of ncBAF activity." (PMID 40181550, 2026). "SMARCB1-deficient tumours possess immune-evading capabilities via PD-L1 overexpression and immune checkpoint activation." (PMID 40422882, 2025). "Upon SMARCB1 loss-of-function, this process is significantly impaired, resulting in the repression of key tumour suppressor and lineage-specific differentiation genes (see Section BAF and Polycomb complex antagonism)." (PMID 40794298, 2025). "Taken together, the development of AT/RT is time-dependent in the sense that a specific developmental time window exists during which the tumour progenitor cell is vulnerable to complete Smarcb1 loss initiating rhabdoid tumour growth." (PMID 40794298, 2025). "Mutations leading to truncated SMARCB1 can result in its exportin-1-mediated mislocalisation in the cytoplasm and hence loss of tumour-suppressive capacity." (PMID 40422882, 2025). "Activation of an embryonic stem cell (ESC)-like signature was associated with rhabdoid histology in these SMARCB1-deficient NPLC-derived tumours." (PMID 40794298, 2025). "In MRTs, the loss of SMARCB1 is not only a marker of tumor progression but also a driving force behind the cellular behaviors that define these cancers, including abnormal growth, resistance to apoptosis, and failure to differentiate." (PMID 40076599, 2025). "ATRT is an aggressive tumor primarily affecting infants, with rare adult cases linked to inactivation of SMARCB1 (INI1) or SMARCA4 (BRG1)." (PMID 40851939, 2025). "This study employs a deep mutational scanning (DMS) approach to explore the functional landscape of SMARCB1, a tumor suppressor, in the context of SMARCB1-deficient cancer cell lines." (PMID 40196006, 2025). "Loss of SMARCB1 activity in hESCs inhibited neural induction during differentiation assays, a finding which is consistent with its role as a tumour suppressor in the central nervous system." (PMID 40794298, 2025). "Further, the AT/RT subgroups also exhibit differences in SMARCB1 mutation patterns, clinical features including patient age, tumour location and neuroradiological imaging results." (PMID 40794298, 2025). "The inactivation of Ezh2 in a conditional mouse model completely blocked tumour formation caused by Smarcb1 inactivation." (PMID 40794298, 2025). "Here, using transcriptomic inference from SMARCB1-deficient tumor cells, we nominate the DNA damage repair kinase ATR as a target for rational EZH2 combination epigenetic therapy." (PMID 40794452, 2025). "ATRTs often exhibit deletions or mutations in the SMARCB1 gene, which is commonly associated with this tumor type." (PMID 41155355, 2025). "We show that missense mutations in the RPT2 domain of SMARCB1 disrupt SMARCB1 tumor suppressor function by destabilizing the SWI/SNF complex." (PMID 40196006, 2025). "Next-generation sequencing revealed two SMARCB1 mutations (M217fs*12, splice site 94-1G>C), with 0 mutations/Mb tumor mutational burden." (PMID 40052132, 2025). "Our results provide new insights into the mutational tolerance and structural vulnerability of SMARCB1, identifying critical functional domains and key residues that govern the tumor suppressor activity of SMARCB1." (PMID 40196006, 2025). "Loss of KTM2A or SMARCB1 disrupts transcriptional regulation within the cells, potentially contributing to the aberrant gene expression profiles observed in tumour cells." (PMID 41247561, 2025). "While the link between SMARCB1 deficiency and enhanced metastatic potential has been explored in several tumour types, this association has been somewhat understudied in RTs." (PMID 40422882, 2025).
tumor (continued). "Tumor DNA methylation profiling was performed for 69 patients with a histologically confirmed diagnosis of ATRT (based on SMARCB1 loss by immunohistochemistry)." (PMID 41008919, 2025). "This is in stark contrast to the involvement of SMARCB1 in the tumorigenesis of highly malignant aggressive tumours such as pediatric AT/RT associated with a very poor prognosis." (PMID 40794298, 2025). "Inhibition of PD-L1 and TIGIT through atezolizumab and tiragolumab, respectively, is being examined in a phase I/II clinical trial for the treatment of relapsed or refractory SMARCB1- or SMARCA4-deficient tumours." (PMID 40422882, 2025). "Sporadic ATRTs are notable for their aggressive behavior and poor prognosis, particularly associated with mutations in the SMARCB1 or SMARCA4 tumor suppressor genes, leading to unchecked cellular proliferation and tumor development." (PMID 41155355, 2025). "The activation of UPR is likely to be a by-product of the MYC-induced hypermetabolic state in the Smarcb1-deficient tumour cells." (PMID 40794298, 2025). "Remarkably, C-terminal truncation of SMARCB1 leads to the unmasking of the nuclear export sequence causing the cytoplasmic localization of SMARCB1 associated with the loss of tumour suppressor function." (PMID 40794298, 2025). "While BAF alterations occur across diverse malignancies and typically in older patients, ATRT in infants and young children is most often driven by biallelic SMARCB1 loss—contrasting with the monoallelic tumor-suppressor patterns common in other cancers." (PMID 41514521, 2025). "A recent publication demonstrated the molecular mechanism of tazemetostat resistance in SMARCB1-deficient tumours." (PMID 40011240, 2025). "ATRT is an aggressive tumor mainly affecting infants, but with rare adult cases linked to inactivation of SMARCB1 (INI1) or SMARCA4 (BRG1)." (PMID 40851939, 2025). "This indicates that patients with RTPS1 remain at elevated risk for developing SMARCB1-deficient tumours after the peak age of MRT in early childhood." (PMID 40794298, 2025). "Tazemetostat shows increased activity in tumors lacking integrase interactor 1 (INI1, also known as SMARCB1), as INI1 loss allows EZH2 to act as an oncogenic driver in tumor cells." (PMID 40076599, 2025). "Malignancy in MRTs is driven by massive changes in the epigenome due to SMARCB1 loss accompanied by changes in the expression of hundreds of genes leading to an undifferentiated tumour phenotype with a very poor prognosis." (PMID 40794298, 2025). "These authors reported two cases of aggressive intraocular tumours in two children with germline SMARCB1 PVs and biallelic SMARCB1 loss in tumour tissue." (PMID 40794298, 2025). "This research describes the cytological and immunohistochemical (IHC) characteristics of an SMARCB1 (INI1)-deficient intrathoracic neoplasm detected in pleural fluid." (PMID 40291911, 2025). "In conclusion, this study provides a comprehensive functional analysis of SMARCB1 variants, identifying key regions and residues involved in its tumor suppressor activity." (PMID 40196006, 2025). "After prioritization, thirteen SMARCB1 amino acid residues intolerant to missense PVs were identified by expression of constructs containing these variants in SMARCB1-deficient tumour cell lines." (PMID 40794298, 2025). "Several of them developed additional primary SMARCB1-deficient tumours after being cured of the initial MRT." (PMID 40794298, 2025). "The tumor exhibited an immunohistochemical profile characterized by a complete loss of INI1 (SMARCB1) expression, coupled with epithelial membrane antigen (EMA), S100, p63, and CK MNF116 positivity." (PMID 40217628, 2025). "The rapid tumor progression highlights the therapeutic challenges posed by SMARCB1-deficient tumors, as supported by evidence showing limited benefit of ifosfamide-based regimens in high-risk MRTs." (PMID 40225550, 2025).
tumor (continued). "ATRT is a rare, aggressive neoplasm predominantly affecting young children and is typically associated with inactivating mutations in the SMARCB1 or SMARCA4 tumor suppressor genes." (PMID 41155355, 2025). "In the tumour tissue of the patient with the 3.1-Mb distal deletion in 22q11.2, complete loss of SMARCB1 expression was observed." (PMID 40794298, 2025). "One notable parameter was the average tumor size, which was similar between both groups with an average of 5 cm, compared to the 7 cm average reported for SMARCB1-deficient carcinomas." (PMID 39590317, 2024). "Although the two patients in our series were PDL1-negative, data from a pediatric series showed PDL1 positivity in 47% of tumor samples with concurrent SMARCB1 loss." (PMID 39125735, 2024). "Overall, these in vivo experimental findings suggest that loss of SMARCB1 increased BLCA tumor growth and metastasis, consistent with the clinical association of low SMARCB1 BLCA tumors with worse outcomes." (PMID 38355560, 2024). "A rare histologic subgroup of SWI/SNF-deficient neoplasms and the subject of our investigation is SMARCB1-deficient sinonasal adenocarcinoma defined by glandular features." (PMID 38085333, 2024). "EZH2 knockdown in SMARCB1 deficient ecMRT tumors decreased the tumor growth rate, while targeting EZH2 with Ribavirin101 or DZNep102 led to increased survival in orthotopic AT/RT xenograft models." (PMID 39465218, 2024). "SWI/SNF-related matrix-associated actin-dependent regulator of chromatin subfamily B member 1 (SMARCB1) is a tumor suppressor gene, and SMARCB1 deficits have been associated with numerous malignant tumors." (PMID 39398818, 2024). "The fact that the AT/RT subgroups are associated with different SMARCB1 alterations suggests that the mutation event itself plays a relevant role in the tumor cell phenotype." (PMID 39465218, 2024). "Two organoid xenografts escaped SMARCB1 KD targeted by their shRNA and showed greater tumor growth compared to controls, reinforcing selective pressure against SMARCB1 loss." (PMID 38472198, 2024). "To identify a novel synthetic lethal target in SMARCB1-deficient cancers, we first established an isogenic cell line model by introducing SMARCB1 cDNA into SMARCB1-deficient JMU-RTK-2 rhabdoid tumor cells." (PMID 38839769, 2024). "To investigate the role of SMARCB1 loss in mediating tumor growth and metastasis, we used CRISPR/Cas9 to knockout (KO) SMARCB1 (from clone C16) in the human T24 BLCA cell line." (PMID 38355560, 2024). "Herein, we report a case of SMARCB1-deficient tumor arising in the parapharyngeal space, treated with radiation alone, with a good sensitivity and response to the radiotherapy." (PMID 39398818, 2024). "TTI-101 durably inhibited in vivo tumor growth throughout the course of drug treatment in both the orthotopic SMARCB1 KO cell line-derived xenograft and the SMARCB1-deficient PDX model." (PMID 38355560, 2024). "Here, we used DNAm data to generate epigenetic age scores and identify opportunities for targeting aging pathways in SMARCB1-deficient neoplasms." (PMID 38879847, 2024). "While the cell-of-origin for these tumor types remains unresolved, it is intriguing that a very similar mutation event in the SMARCB1 locus is able to promote tumor types with differing prognoses." (PMID 39465218, 2024). "Within these tumors, SMARCB1 acts as a tumor suppressor and presents loss of function of both alleles, resulting in the loss of expression of this mSWI/SNF subunit defining these tumors." (PMID 39542244, 2024). "SMARCB1‐deficient tumors show infiltration by subpopulations of clonally expanded T cells, suggesting a tumor-specific immune response." (PMID 38217014, 2024). "Partial loss of SMARCB1/INI1 was correlated with cervical–thoracic–lumbar tumor location (p = 0.033) and inadequate surgical margins (p = 0.007), possibly due to the high degree of tumor invasiveness in this site." (PMID 39199581, 2024).